SLC25A2 (solute carrier family 25 member 2)
Description:
Mitochondrial transporter of the positively charged amino acids ornithine, lysine and arginine, and the neutral amino acid citrulline. In addition, transports the basic amino acids histidine, homoarginine, and asymmetric dimethylarginine (aDMA), but not symmetric DMA, and the D-forms of lysine, arginine, ornithine and histidine. Functions by both counter-exchange and uniport mechanisms.
Synonyms: ORNT2
Tractability: Antibody: UniProt predicts a signal peptide or a membrane-spanning region.
Gene: Protein-coding gene on chromosome 5 (141,302,635 to 141,304,049, reverse strand). Ensembl gene ENSG00000120329.
Subcellular location: Mitochondrion membrane; Mitochondrion inner membrane
Pathways (Reactome):
Metabolism: Urea cycle
Gene Ontology:
Molecular function: L-arginine transmembrane transporter activity; L-lysine transmembrane transporter activity; L-ornithine transmembrane transporter activity; protein binding
Biological process: L-arginine transmembrane transport; L-lysine transmembrane transport; L-ornithine transmembrane transport; mitochondrial L-ornithine transmembrane transport; ornithine metabolic process; urea cycle
Cellular component: mitochondrial membrane; mitochondrion; mitochondrial inner membrane
Genetic constraint (gnomAD): Loss-of-function variants: 14 observed, 20.66 expected, observed/expected ratio (o/e) 0.68, 90% interval 0.45 to 1.06. The upper end of that interval is the gene's LOEUF score, 1.06, which puts it in group 4 of 6, group 1 being the genes least tolerant of losing a copy. Missense variants: 356 observed, 399 expected, observed/expected ratio (o/e) 0.89, 90% interval 0.82 to 0.97. Synonymous variants: 158 observed, 163.03 expected, observed/expected ratio (o/e) 0.97, 90% interval 0.85 to 1.11.
Homologues: Orthologues: macaque SLC25A2 (98% identical), dog SLC25A2 (87% identical), rabbit SLC25A2 (86% identical), rat Taf7 (76% identical), mouse Slc25a2 (69% identical). Paralogues in human: SLC25A15 (87% identical), SLC25A20 (32% identical), SLC25A29 (30% identical), SLC25A12 (29% identical), SLC25A45 (28% identical), SLC25A13 (27% identical), SLC25A47 (27% identical), SLC25A48 (27% identical), SLC25A21 (25% identical), UCP2 (24% identical), SLC25A16 (23% identical), SLC25A18 (23% identical), and 37 more.
Diseases named in the same sentence as SLC25A2 in open-access papers:
SLC25A2 is named in the same sentence as 12 diseases in open-access papers, as found by Europe PMC text mining. Sharing a sentence is not in itself a finding about the gene and the disease. The quoted sentences say what the papers report.
tumours (1 paper, 2009). "By contrast, expression of non-PCDH genes at 5q31 (TAF7 and SLC25A2) was strongly linked to methylation status in WTs, and the transcriptional status of unmethylated genes flanking the LRES was unchanged in tumours." (PMID 19956686, 2009). "Two non-PCDH genes are situated within the methylated domain; SLC25A2 was constitutively methylated in both normal tissues and tumours and TAF7 was constitutively unmethylated." (PMID 19956686, 2009).
SLC25A2 also shares sentences with these, for which no sentence is quoted: Hyperammonemia (2 papers); atrial fibrillation (1); coronary artery disease (1); delirium (1); gastric cancer (1); glioma (1); gout (1); heart failure (1); Obesity (1); type 2 diabetes (1); urea cycle disorder (1).